KLK7 (kallikrein related peptidase 7)
Diseases named in the same sentence as KLK7 in open-access papers (continued):
Sharing a sentence is not in itself a finding about the gene and the disease.
cancer (36 papers, 2004 to 2026). A tumor composed of atypical neoplastic, often pleomorphic cells that invade other tissues. "For example, the upregulation of KLK7, a gene encoding kallikrein-related peptidase 7, has been linked to the promotion of cell proliferation and invasion in several types of cancer." (PMID 37641095, 2023). "A significant association between KLK7 positivity and low grade could therefore be expected in these cancers." (PMID 38961454, 2024). "The mechanisms underlying the KLK7‐mediated increase in cell motility and invasion remain unknown but might be directed by modulating other enzymatic pathways important in cancer metastasis." (PMID 28636767, 2017). "This observed KLK7‐induced effect on the dissemination process is consistent with the described role of KLK7 in cell invasion and its association with unfavorable prognosis in several types of cancers." (PMID 28636767, 2017). "In addition, upregulation of KLK7 expression was associated with age and cancer stage." (PMID 33336051, 2020). "Nonetheless, the possible molecular pathways leading to increased KLK7 levels during cancer development need more fundamental and clinical studies for investigation." (PMID 39991575, 2025). "Researchers examined the impact of KLK7 on the cancer characteristics of PTC and explored if KLK7 influences the Epithelial-mesenchymal transition (EMT) process via the MAPK/ERK pathway in PTC using methods like immunohistochemistry and growth curve analysis." (PMID 39991575, 2025). "While earlier studies have established a broad link between KLKs and cancer progression 12-14, few have specifically identified the mechanistic pathways through which KLK7 influences PTC progression." (PMID 39991575, 2025). "In cancer, KLK7 overexpression was suggested to represent a route for metastasis through cleavage of cell junction and extracellular matrix proteins of cancer cells." (PMID 38961454, 2024). "KLK7 facilitates various processes involved in cancer, such as cell growth, proliferation, migration, angiogenesis via hydrolyzing cytokines, ECM, and membrane proteins." (PMID 36905477, 2023). "The potential of KLK5 and KLK7 as therapeutic targets in cancer has led to advances in the development of the first generation of KLK-based inhibitors." (PMID 33588911, 2021). "In our report, we demonstrated that the expression of KLK7 was higher in a range of 41–60 years cancer stage." (PMID 33336051, 2020). "Especially, in different types of cancer, including breast, ovarian, pancreatic, colorectal, and lung tumors, expression of KLK7 was shown to be dysregulated." (PMID 33087135, 2020). "Because KLK7 has been proposed to act as a proliferative factor in many cancer types, we next investigated the effect of KLK7 on mitogen‐activated protein kinase (MAP kinase) (ERK1/2) phosphorylation, an upstream kinase in the proliferation pathways." (PMID 28636767, 2017). "As KLK7 is only expressed in a limited number of normal tissues and de-novo expression can occur in cancer, KLK7 may represent a suitable drug target for the treatment of cancer." (PMID 38961454, 2024). "Our data markedly expand the available data on KLK7 protein expression in cancer." (PMID 38961454, 2024). "Investigation focused on the functional mechanism underlying KLK7 suggested that it could cleave pro-MMP9-generating active MMP9 and induce the shedding of cell adhesion proteins so as to mediate cancer cell proliferation and invasion." (PMID 32076707, 2020). "The KLK7 expression showed upregulated in cancer tissues compared to that in normal tissues." (PMID 33336051, 2020). "In survival analysis, we confirmed one kallikrein (KLK6) that had previously been associated with poor survival and identified one kallikrein (KLK7) that previously had not been implicated in prognosis of this cancer." (PMID 29707153, 2018).
cancer (continued). "Therefore, we expect our study to advance the rational design of inhibitors targeting kallikrein-related peptidase 7, an emerging drug target involved in several skin diseases as well as cancer." (PMID 29210603, 2018). "The observed inhibitory effect on cell proliferation suggests that KLK7 may exert opposite effects depending on the cancer cell type." (PMID 28636767, 2017). "KLK7 involvement in cell growth has also been demonstrated in different cancers." (PMID 28636767, 2017). "Notably, expression of KLK7 mRNA was regulated by methylation of histones in cancer cell lines." (PMID 29311134, 2018). "Using the KLK-CANMAP, a tool that includes several other cancer datasets, we again found the KLK6, KLK7, KLK8 and KLK10 cluster, with the exception of KLK11, which was upregulated in PDAC compared to normal pancreas tissues." (PMID 34439122, 2021). "Subpopulation B consisted of 121 cells (29.1%) and showed overexpression of 13 genes, including seven cancer genes (HSPB1, ANXA1, SLPI, KRT8, KRT19, KLK7, and ABL2) and several Keratin genes (KRT8, KRT7, KRT19, and KRT6B)." (PMID 28794488, 2017). "The mRNA expression status of the KLK5, KLK6, KLK7, KLK8 and KLK9 has been extensively studied in cancer." (PMID 29229980, 2017). "Like the KLK7 spheroids the KLK4-MCAs were able to invade into mesothelial cell monolayers and produced larger cancer cell foci than those formed by vector and native SKOV-3 cells." (PMID 23451143, 2013). "This is in agreement with our unpublished data showing overexpression of several kallikreins (KLK6, KLK7, KLK10) on the mRNA level of cancer samples as compared with their paired normal colon mucosa." (PMID 19367279, 2009). "However, the literature reveals a gap in the targeted exploration of KLK7 within PTC, particularly in relation to its regulatory mechanisms, and direct impact on cancer cell behavior." (PMID 39991575, 2025). "Targeting KLK5, KLK7, and KLK14 may pave the way for novel treatments that prevent cancer progression." (PMID 40753921, 2025). "However, our own analyses of cancer entities with data on histomorphological features of malignancy did not provide evidence for a paramount prognostic impact of KLK7 expression on cancer malignancy." (PMID 38961454, 2024). "Moreover, in several cancer types KLK5 and KLK7 co-expression has been observed." (PMID 33087135, 2020). "Both KLK7 and KLK10 expressions were significantly higher in the cancer group than those of the non-cancer group (P < 0.05)." (PMID 37868053, 2023).
metabolic disease (5 papers, 2013 to 2025). A congenital disorder (due to inherited enzyme abnormality) or acquired (due to failure of a metabolically important organ) disorder resulting from an abnormal metabolic process. "Kallikrein 7 (KLK7) is the first known protease target inhibited by vaspin and a potential target for the treatment of metabolic disorders." (PMID 28932870, 2018). "The authors propose that inhibitors of KLK7 could be beneficial for metabolic disease." (PMID 37358498, 2023).
cardiovascular disease (1 paper, 2025). "Furthermore, ECI2, KLK7, and SPINK6 appear to be linked to other forms of cardiovascular disease rather than CIHD." (PMID 41283645, 2025).
head and neck tumors (1 paper, 2021). "Although in this study we focused on protein-coding genes, we noted top two highly up regulated non-coding transcripts in KLK6 high group samples, i.e., CTB-147C22.8 and CTB147C22, which were reported to be co-expressed with kallikrein genes KLK5, KLK6, and KLK7 in HPV16+ head and neck tumors." (PMID 34065672, 2021).
KLK7 also shares sentences with these, for which no sentence is quoted: cervical adenocarcinoma (3 papers); eczema (3); gastric cancer (3); Hyperglycemia (2); ichthyosis (2); lung carcinoma (2); triple-negative breast carcinoma (2); adenocarcinomas of the (1); Allergy (1); anaplastic breast carcinoma (1); ankylosing spondylitis (1); cervical intraepithelial neoplasia (1); cervicitis (1); colorectal adenocarcinoma (1); coronary artery disease (1); diabetes (1); endometrium cancers (1); esophageal tumors (1); infertile (1); injury (1); malaria (1); mental illness (1); metastatic melanoma (1); metastatic tumors (1); neurological disorders (1); oral squamous cell carcinomas (1); osteogenesis imperfecta (1); ovarian endometrioid adenocarcinoma (1); Palmoplantar keratoderma (1); pancreatic ductal adenocarcinoma (1).
A further 6 diseases each share a sentence with KLK7 in 1 paper.